RACK1 (receptor for activated C kinase 1)
Diseases named in the same sentence as RACK1 in open-access papers (continued):
Sharing a sentence is not in itself a finding about the gene and the disease.
hepatocellular carcinoma (31 papers, 2011 to 2025). A malignant tumor that arises from hepatocytes. "For example, increased RACK1 O‐GlcNAcylation was detected in patients with hepatocellular carcinoma, which was associated with poor prognosis after chemotherapy." (PMID 38451046, 2024). "With regards to Nanog transactivation, the knockdown of RACK1 significantly impeded the process in hepatocellular carcinoma HuH7 cells, while overexpression of RACK1 notably augmented it." (PMID 40034124, 2025). "Elevated levels of RACK1 mRNA or protein have been observed in clinical hepatocellular carcinoma samples by different research groups." (PMID 40034124, 2025). "RACK1 is markedly upregulated in several cancers like breast, colorectal adenocarcinoma, cervical cancer, hepatocellular carcinoma, and prostate cancer." (PMID 39458945, 2024). "Studies have identified that RACK1 plays an important role in different types of human cancers, such as breast cancer, hepatocellular carcinoma, melanoma, and lung adenocarcinoma." (PMID 35101055, 2022). "On the other hand, RACK1 is recognized as an oncogene and promotes cell proliferation in hepatocellular cancer." (PMID 35101055, 2022). "Rack1 elevation enhances chemoresistance in leukemia, hepatocellular carcinoma, and esophageal cancer; Rack1 overexpression promotes targeted therapy resistance in gastrointestinal stromal tumor." (PMID 31113450, 2019). "Instead, we have found that RACK1 enhances JNK activation by directly binding to MAP2K MKK7 in human hepatocellular carcinoma cells." (PMID 26381936, 2015). "RACK1 enhances Nanog expression in both hepatocellular carcinoma cells and mouse ESCs." (PMID 40034124, 2025). "Furthermore, O‐GlcNAcylation of RACK1 has been shown to promote tumour development, with elevated RACK1 O‐GlcNAcylation levels detected in hepatocellular carcinoma patient liver samples, correlating with tumour proliferation and recurrence." (PMID 38451046, 2024). "It was previously reported that O-GlcNA acylation of RACK1 at serine 122 enhances its stability, ribosome localization and interaction with the protein kinase PKCβII, thereby promoting oncogenic translation and progression of hepatocellular carcinoma." (PMID 37828084, 2023). "In another study, interaction between IRE1α and RACK1 was crucial for the activation of IRE1α/XBP1 signalling upon unfolded protein response induced by sorafenib in hepatocellular carcinoma cells, further supporting the interconnection between MYC signalling and ER processes." (PMID 32878211, 2020). "Additionally, a recent study has shown that Rack1 is involved in drug resistance in hepatocellular carcinoma." (PMID 27754360, 2016). "RACK1 has been related and even suggested as marker for mammalian cell proliferative processes since early reports of its overexpression in breast, lung and hepatocellular carcinoma." (PMID 26697044, 2015). "And genetic ablation of receptor for activated C kinase 1 (RACK1) O-GlcNAcylation at Ser122 dramatically suppressed angiogenesis in hepatocellular carcinoma (HCC)." (PMID 35432358, 2022). "In addition, RACK1 expression was frequently found to be reduced in hepatocellular carcinoma." (PMID 21935400, 2011). "While RACK1 expression was essentially normal in most cancers, it was frequently reduced in hepatocellular carcinoma (HCC), consistent with a previous report." (PMID 21935400, 2011). "O-GlcNAc-modified RACK1 enhances ribosome binding and interaction with PRKCB, thereby increasing the translation of potent oncogenes in hepatoma cells." (PMID 38993567, 2024). "As for the hepatitis B virus, its core protein has been shown to disrupt the interaction between MKK7 and RACK1, thereby enhancing tumor necrosis factor-α (TNF-α)-induced apoptosis in HepG2 human hepatoma cells." (PMID 35265209, 2022). "In addition, our previous study indicates that RACK1 enhances JNK activation by directly binding to and facilitating the interaction between MKK7 and upstream MAP3Ks in human hepatocellular carcinoma cells." (PMID 26381936, 2015).
lung carcinoma (19 papers, 2012 to 2025). "Intriguingly, RACK1 affects cancer progression in a tissue-dependent manner; while it promotes breast and lung cancers, it suppresses gastric tumors." (PMID 39086661, 2024). "Of these proteins, HSP90AA1, ITGB1, cytokeratin-8 (KRT8) and receptor for activated C-kinase (RACK1) are identified prognostic markers for overall survival in solid malignancies including lung cancer." (PMID 33777753, 2021). "Several studies indicate that RACK1 plays an important role in cancer progression and that its expression is up-regulated during angiogenesis in several kinds of carcinomas, including lung cancer." (PMID 25686824, 2015). "Elevated levels of Rack1 expression have been detected in lung cancer, and silencing of RACK1 expression has led to suppressed cancer cell growth and invasion both in vitro and in vivo." (PMID 23866081, 2013). "As expected, RACK1 could be ubiquitinated in lung cancer cells, and PHB2 overexpression reduced RACK1 ubiquitination." (PMID 33537079, 2021). "PKM2 could form complexes with FGFR1 and RACK1 to participate in the occurrence and development of lung cancer." (PMID 33193873, 2020). "One possibility that could explain these discrepancies is the interface of Eph receptors with downstream networks that regulate tumorigenicity, such as that between EphB3 and the PP2A/RACK1/Akt axis in lung cancer." (PMID 23844053, 2013). "However, the context-dependent role of RACK1 in lung cancer remains controversial." (PMID 35101055, 2022). "To further determine the relationship between CPNE3 and RACK1, we collected 12 pairs of NSCLC lung cancer tissue and corresponding adjacent tissue samples." (PMID 41190648, 2025). "Furthermore, RACK1 is a regulatory cofactor of the phosphatidylcholine translocator ABCB4, which is also induced by CBD and has been reported to suppress colony formation and proliferation of lung cancer cells." (PMID 40429863, 2025). "However a non-canonical GLI-1 activation likely occurs in a Rack1-dependent manner in NSCLC patients as a proposed necessary step for lung cancer tumorigenicity." (PMID 28978016, 2017).
viral infection (19 papers, 2015 to 2025). "First, we found a significant inhibitory effect of PRV on the expression of RACK1, IFN‐β, ISG15, and ISG20 in cells during the late phase of viral infection, indicating a potential association between RACK1, IFN‐I pathway, and PRV infection." (PMID 41395239, 2025). "RACK1 levels were increased after viral infection and the increase in RACK1 was proportionally associated with the MOI of virus." (PMID 31143369, 2019). "RACK1 has been implicated as a key modulator of IFN‐I signaling during viral infections." (PMID 41395239, 2025). "Paradoxically, Thr50 phosphorylation can also enhance viral infection by facilitating RACK1 interaction with interferon transcriptional factor IRF3, suppressing IRF3 phosphorylation and subsequent interferon synthesis." (PMID 41373878, 2025). "Receptor of activated protein kinase C 1 (RACK1) is initially known as a receptor for protein kinase C, and recent studies indicate that RACK1 can also play critical roles in various virus infections." (PMID 41395239, 2025). "Studies indicate that RACK1 plays a crucial role in cancer progression, NF-κB activation, and various viral infections." (PMID 41472131, 2025). "The results demonstrated that the anti-IBV N antibody efficiently co-precipitated N protein and endogenous RACK1, providing evidence of specific binding during the virus infection process." (PMID 39602452, 2024). "In contrast to its role in viral infection, RACK1 protects cells from infection byPasteurella multocida, a gram-negative bacterium, via activation of the NLRP3 inflammasome." (PMID 38813597, 2024). "RACK1 has been identified as a critical host factor for viral replication, especially during viral infection." (PMID 39334337, 2024). "Upon viral infection, RACK1 remodels ribosomes so that they become optimal for translating viral mRNAs but not host mRNAs." (PMID 39766256, 2024). "Since ROS is essential for the infection process, downregulation of RACK1 significantly limits viral infection." (PMID 36768198, 2023). "Other cytoplasmic proteins with altered localization during viral infection include oxysterol-binding protein–related proteins (ORPs), a yeast RNA-binding protein (LSm1), receptor for activated C kinase 1 (RACK1), and a proteasome protein (20S α5)." (PMID 33920930, 2021). "RACK1 was induced at the very beginning of the viral infection (2 hpi), as can be seen by comparing the levels of RACK1 after viral infection to that of 0 hpi." (PMID 31143369, 2019). "Cells were cultured and infected with scramble shRNA or Rack1-targeting shRNA, on technical triplicates of viral infection." (PMID 28765829, 2017). "Previous studies revealed that RACK1 played critical roles in regulating viral infections, which could either enhance the proliferation of LCDV and DENV or inhibit the proliferation of CSFV." (PMID 41395239, 2025). "Several studies have demonstrated the critical roles of RACK1 in viral infections." (PMID 41395239, 2025). "Studies showed that RACK1 could function as a significant host regulator during viral infection, exhibiting divergent roles across different viruses." (PMID 41395239, 2025). "Additionally, the expression of the IBV N protein, viral genome and transcripts, and released virus particles were all reduced in RACK1 knockdown cells, highlighting the importance of RACK1 in virus infection." (PMID 39602452, 2024). "If RACK1 is depleted, viral translation is impaired, which result in unsuccessful viral infection." (PMID 36768198, 2023). "Since RACK1 is an important factor for protein translation, we wondered whether RACK1 expression is regulated by viral infection." (PMID 31143369, 2019). "RACK1 (receptor of activated protein C kinase 1) was first identified as a receptor for protein kinase C, with increasing evidence showing that the functionally conserved RACK1 plays important roles in cancer development, NF-κB activation and various virus infections." (PMID 29445214, 2018).
viral infection (continued). "Apart from cancer progression, interplay between integrins, kindlin-3 and RACK1 may also be important in viral infections." (PMID 26677948, 2015). "Furthermore, RACK1 could also regulate several innate immune pathways during viral infections, such as the IFN‐I signaling pathway and the NF‐κB signaling pathway." (PMID 41395239, 2025). "We further examined whether IBV N binds to endogenous RACK1 during virus infection." (PMID 39602452, 2024). "Interestingly, recent studies indicate that ZNF598 and RACK1 may also suppress the innate immune response to viral infection via the RIG-I-MAVS signaling pathway, responsible for sensing cytosolic RNAs." (PMID 34111399, 2021). "In addition, it has been reported that RACK1 may play a role in the virus infection and immune system." (PMID 27170279, 2016). "The presence of both RACK1 and PKCα/β is required for the phosphorylation of NUP62 and suppression of antiviral gene expression, thereby benefiting virus infection." (PMID 39602452, 2024). "Another hub kinase RACK1 (GNB2L1), is a highly conserved intracellular adaptor protein and involved in several biological processes including virus infection, cell migration, neural development, and angiogenesis." (PMID 36590916, 2022).
non-small cell lung carcinoma (18 papers, 2008 to 2025). A group of at least three distinct histological types of lung cancer, including non-small cell squamous cell carcinoma, adenocarcinoma, and large cell carcinoma. "Receptor of activated kinase 1 (RACK1) is overexpressed in non-small cell lung cancer, and the level of RACK1 is clearly associated with the pathological characteristics, such as tumour stage, differentiation and metastasis, of non-small cell lung cancer patients." (PMID 29899399, 2018). "CPNE3 promotes migration and invasion in non-small cell lung cancer by interacting with RACK1 via FAK signaling activation." (PMID 34367247, 2021). "CPNE3 can promote migration and invasion in non-small cell lung cancer by interacting with RACK1 via FAK signaling activation." (PMID 34367247, 2021). "In non-small-cell lung cancer, RACK1 served as an oncogene and silence of RACK1 resulted in inhibition of tumor growth and metastasis through the sonic hedgehog signaling pathway." (PMID 31949482, 2020). "RACK1 promotes the progression and metastasis of non-small cell lung cancers that primarily involve activation of the Shh pathway, in which RACK1 interacts with activated Smo to initiate Gli1 transcription in non-small cell lung cancer cells." (PMID 29899399, 2018). "In this report, we demonstrate that RACK1 regulates cell growth and cell cycle progression in human non-small-cell lung cancer by mediating MCM7 phosphorylation through an MCM7/RACK1/Akt signaling complex." (PMID 28465488, 2017). "RACK1 mRNA was found to be strongly expressed in five non-small cell lung carcinomas, mainly in the endothelium of large vessels." (PMID 18442364, 2008). "However, in non-small cell lung cancer, RACK1 mediates the assembly of the RACK1–PP2A–Akt signaling complex in response to EphB3 activation, leading to decreased Akt phosphorylation and the inhibition of cell migration." (PMID 37296580, 2023). "Moreover, MCM7 participated in regulating cell growth and cell cycle progression in non-small-cell lung cancer through a MCM7/RACK1/Akt signaling complex." (PMID 33505310, 2020).
colon cancer (17 papers, 2013 to 2025). "In malignant colon cancer cells, it has been found that association of Rack1 with FEM1b mediates downregulation of FEM1b protein level by promoting ubiquitination of FEM1b8." (PMID 27644318, 2016). "Additionally, receptor for activated C kinase 1 (RACK1), a commonly found mutation in cancer, induced autophagy and promoted proliferation while inhibiting apoptosis in colon cancer." (PMID 31671556, 2019). "Therefore, we investigated the association of RACK1-induced autophagy with the proliferation and apoptosis of colon cancer cells." (PMID 30451832, 2018). "As senescence is characterized by the irreversible loss of proliferation and alongside apoptosis, high RACK1 expression may be involved in the pathogenesis of colon cancer." (PMID 30451832, 2018). "RACK1 interacts with the apoptotic protein Fem1b to promote its ubiquitination level in colon cancer cells; downregulation of RACK1 leads to FEM1B‐mediated apoptosis." (PMID 39425259, 2025). "More recently, RACK1 was demonstrated to be involved in the proliferation and survival of colon cancer cells by facilitating autophagy initiation." (PMID 38532543, 2024). "An experiment on colon cancer revealed that RACK1‐induced autophagy promoted the proliferation of colon cancer cells." (PMID 38451046, 2024). "FEM1B has a pro-apoptotic function in colon cancer cells, which is regulated by receptor for activated C kinase (RACK1)." (PMID 39140134, 2024). "RACK1 is thought to be an oncogene in colon cancer, and RACK1-induced autophagy promotes the survival and proliferation in colon cancer cells." (PMID 36690709, 2023). "On the one hand, RACK1-induced autophagy increases colon cancer cell proliferation and inhibits colon cancer cell apoptosis." (PMID 30962803, 2019). "We observed that RACK1 overexpression upregulated while RACK1 knockdown downregulated phospho-JNK level in the colon cancer cells." (PMID 30451832, 2018). "Collectively, these results demonstrate that RACK1 promotes colon cancer cell proliferation and inhibits colon cancer cell apoptosis." (PMID 30451832, 2018). "The results suggest that RACK1-induced-autophagy promotes colon cancer cell proliferation, inhibits colon cancer cell apoptosis." (PMID 30451832, 2018). "Reexpression of RACK1 in the RACK1 KD colon cancer cells rescued cell proliferation, cell cycle distribution and apoptosis, indicating these phenotypes not due to off-target effects." (PMID 30451832, 2018). "We observed that BAF further increased the number of EGFP-LC3 puncta induced by RACK1 OE in the colon cancer cells." (PMID 30451832, 2018). "We first detected RACK1 expression levels in five colon cancer cell lines (HT-29, SW480, SW620, HCT116, and HRT18) and four fresh NCM by western blot." (PMID 30451832, 2018). "Although other groups have studied the roles of RACK1 in colon cancer, the results are controversial." (PMID 30451832, 2018). "In the context of colon cancer, RACK1 expression is shown to inhibit cancer cell growth by delaying cell-cycle progression and promoting apoptosis." (PMID 30112187, 2018). "BAF further increased the levels of LC3-II induced by RACK1 overexpression in the colon cancer cells." (PMID 30451832, 2018). "The result showed that colon cancer patients with higher RACK1 levels had significantly poorer overall survival (OS) versus patients with lower RACK1 levels." (PMID 30451832, 2018). "CCK-8, plate colony formation, and EdU incorporation labeling assay showed that both siRNAs significantly decreased RACK1 OE colon cancer cells proliferation as compared with control siRNA." (PMID 30451832, 2018). "With a combination of loss-of-function and gain-of-function approaches, we observed that RACK1 promoted colon cancer cell proliferation, inhibited colon cancer cell apoptosis, and enhanced the anchorage-independent and xenograft growth of colon cancer cells." (PMID 30451832, 2018).